GZMB (granzyme B)
Diseases named in the same sentence as GZMB in open-access papers (continued):
Sharing a sentence is not in itself a finding about the gene and the disease.
pancreatic cancer (continued). "To confirm whether degranulation of perforin and granzyme-B changes when NK cells attack HER2-high-expressing human pancreatic cancer cell line in the presence of Tmab and/or αCD137, we stained intracellular perforin, granzyme-B and cell surface CD69 of NK cells." (PMID 30596643, 2018). "aCD40 treatment significantly increased tumoral expression of CCL5, potentially contributing to the recruitment of Granzyme B + CD4 + T cells from TDLNs to the tumor bed, as previously reported in pancreatic cancer models." (PMID 40585246, 2025). "Recent investigations into anti-tumor therapies have revealed that vaccine-induced CD8+ T cells, particularly those expressing granzyme B (GZMB), exhibit significant anti-tumor efficacy in the context of pancreatic cancer treatment." (PMID 41446025, 2025). "In GR-knockdown or mifepristone-treated HY24409 pancreatic tumors, knockdown of B2M depleted surface MHC-I in vivo, decreased the percentages of tumor-infiltrating CD8+ T cells and granzyme B+ CTLs, and rescued tumor growth." (PMID 34873175, 2021). "Moreover, a significantly higher frequency of T-cells (CD4+, CD8+) and NK-cells producing perforin and granzyme B compared with healthy controls were noted, which might be related to the presence of tumor antigen-specific T cells as reported in pancreatic cancer patients." (PMID 28099502, 2017). "Moreover, immunofluorescence staining for CD8 and GZMB revealed a significant augmentation of GZMB+CD8+ T cells in CRC or pancreatic cancer patients with low expression of STK24." (PMID 38229183, 2024). "In the absence of Cxcr3, splenic Klrg1 + GzmB + antitumor T cells wain while pancreatic cancer disseminates suggesting a role for these cells in eliminating circulating metastatic tumor cells." (PMID 36472588, 2023). "Furthermore, CALR was significantly correlated with key immunity‐killing molecules, including PRF1, GZMB, and IFNG in pancreatic cancer." (PMID 32508042, 2020). "The decreased percentages of NK cells positive for Perforin and Granzyme-B after exposure to SW1990 and BxPc-3 suggested that pancreatic cancer cells could reduce the cytotoxic activity of NK cells in vitro." (PMID 25274283, 2014). "In this process, the upregulation of some cytotoxic effector molecules (such as perforin and granzyme B) and IFN-γ would help to the killing efficacy on pancreatic cancer cells, which may be vital mechanisms for DHA to enhance the anti-tumor effect of pancreatic cancer cells." (PMID 33613116, 2021). "This analysis revealed that in pancreatic tumors generated by HY24409 cells, either GR knockdown or mifepristone treatment significantly increased the abundance and activity of CTLs, as gauged by CD8 (a marker of CTLs) and granzyme B (a marker of CTL activity), respectively." (PMID 34873175, 2021). "Neutrophils isolated from orthotopic pancreatic tumors accelerated CD8+ T-cell dysfunction, defined as the increased percentage of PD1+TIM3+ cells, and inhibited Granzyme B and IFN-γ production, whereas PB neutrophils did not." (PMID 39261943, 2024). "Lastly, although the authors observed inverse correlations between EPHA2 and CTL gene signatures in human pancreatic cancer, we did not discover any consistent trends between EPHA2 and CD3E, CD8B, GZMA, GZMB, PRF1, or IFNG expression from the TCGA lung adenocarcinoma dataset." (PMID 40867322, 2025).
gastric cancer (29 papers, 2013 to 2025). A primary or metastatic malignant neoplasm involving the stomach. "Our research showed that CCR8+ Tregs localize to the tumor invasion boundary in gastric cancer and can suppress the proliferation and GzmB expression of closely infiltrating CD8+ T cells." (PMID 41323783, 2025). "In this study, we analyzed the infiltration of CCR8+ Tregs and GzmB+ CD8+ T cells in gastric cancer tissues using IHC dual staining and evaluated their association with tumor stage, prognosis, and spatial distribution." (PMID 41323783, 2025). "Recent research has focused on GZMB in the context of gastric cancer (GC), where its expression patterns and functions are being analyzed." (PMID 40766321, 2025). "On the contrary, overexpression of GZMB by plasmid transfection increases these malignant properties, highlighting its role as a promoter of growth and migration in gastric cancer, which has been confirmed in both in vitro and in vivo studies." (PMID 40766321, 2025). "There were 3, 2, 2 and 2 articles investigated CD20+, CD45RO+, Granzyme B+ and T-bet+ TILs in patients with gastric cancer, respectively." (PMID 28915679, 2017). "Furthermore, the use of gastric cancer exosomal THBS1 to enhance production of IFN-γ, TNF-α, perforin, and granzyme B in vitro, to ultimately elevate the killing of gastric cancer cells by Vδ2 T cells in vivo, has yielded successful preclinical trials." (PMID 40148988, 2025). "To further confirm the finding that more activated CD8+ T cells with high cytotoxicity infiltrated into adipose tissue during CAC development, we collected adipose tissues from another 8 patients with gastric cancer undergoing surgical therapy and stained the GZMB+ cells by immunohistochemistry." (PMID 36376273, 2022). "A correlation analysis of the gastric mucosal microbiome in 170 GC tumor tissues and matched non-tumor tissues with immune-activated related transcripts revealed that Akkermansia muciniphila may play a role in modulating the expression of Granzyme B in the gastric cancer mucosal microenvironment." (PMID 40529304, 2025). "We examined continuous tissue sections from 80 gastric cancer patients using dual staining for CCR8/Foxp3 and GzmB/CD8." (PMID 41323783, 2025). "Importantly, prior chemotherapy may impact granzyme B concentrations, as seen in a cohort of patients with gastric cancer, where those receiving prior chemotherapy (n = 49) had significantly lower mean serum granzyme B levels compared to chemotherapy‐naive patients (n = 38) (9.68 vs." (PMID 39162097, 2024). "Granzyme B has also been reported to promote proliferation, migration, and EMT processes in gastric cancer." (PMID 39684816, 2024). "In contrast, gastric cancer cell-derived exosomes enriched with THBS1 enhanced Vγ9Vδ2 T cell cytotoxicity against gastric cancer, increasing the production of IFN-γ, TNF-α, perforin, and granzyme B both in vivo and in vitro." (PMID 39748921, 2024). "In gastric cancer patients, a high level of PD-L1 carried by exosomes was correlated with decreased CD4+and CD8+ T cell infiltration shown by a reduction of granzyme B (GzmB) secretion in these cells." (PMID 36438660, 2022). "Our current results from the immunohistological analysis of human gastric cancer tissues suggest that CCR8+ Tregs may inhibit the proliferation and GzmB expression of surrounding CD8+ T cells, leading to the suppression of antitumor immunity." (PMID 41323783, 2025). "Furthermore, MDSCs from humans with gastric cancer were shown to suppress CD8+ T-lymphocyte function by decreasing the IFN-γ and GZMB expression via arginase production." (PMID 35878391, 2022). "Toll-like receptor 2 (TLR2) was down-regulated in CD8+ T cells of gastric cancer patients, and TLR2 activation could increase the expression of perforin and granzyme B in CD8+ T cells and enhance CD8+ T cells cytotoxicity." (PMID 36341377, 2022).
gastric cancer (continued). "In exhausted T cells, these gene markers (PD1, CTLA4, LAG3, TIM3 and GZMB) were consistently significantly correlated with the expression of CLDN10, which further suggested that the expression level of CLDN10 in gastric cancer is related to immune infiltration." (PMID 34721537, 2021). "In vivo experiments further revealed that KHSRP silencing markedly increased the infiltration of CD4+, CD8+, Granzyme B+, IFN-γ+, and TNF-α+ cells within the tumor, suggesting that KHSRP could serve as a potential prognostic marker and therapeutic target for gastric cancer." (PMID 39866240, 2025). "In this study, five crucial immunophenotype‐related molecules (WARS, UBE2L6, GZMB, BATF2, and LAG‐3) in the TME are determined in five public gastric cancer (GC) datasets (n = 1426) and an in‐house sequencing dataset (n = 79)." (PMID 36998102, 2023).
glioma (28 papers, 2013 to 2025). A benign or malignant brain and spinal cord tumor that arises from glial cells (astrocytes, oligodendrocytes, ependymal cells). "It has been reported that in CHMP5-deficient glioma cells, both the granzyme B/perforin apoptotic pathway and the apoptosis-inducing factor-mediated necrosis pathway are activated, independently of the intrinsic and extrinsic apoptotic pathways." (PMID 36518671, 2022). "Increases of IFN-γ and Granzyme B underlying CCR5+CD38+HLA-DR+CD8+ T cell activation were observed after co-culturing with glioma cells." (PMID 31649684, 2019). "The animal experiments here demonstrate that BV2 co‐implanted tumors exhibit high CD8+ T cell infiltration and increased Granzyme B expression, indicating that tumor‐associated microglia can enhance T cell infiltration and cytotoxic activity, modulating antitumor immunity against gliomas." (PMID 40747560, 2025). "Subsequently, we examined the correlation between Kcr levels and glioma grade in human glioma samples and observed a correlation between Kcr and the expression levels of PD-1 and GZMB in the glioma microenvironment." (PMID 40636690, 2025). "ChIP-seq and qPCR demonstrated that reduced crotonylation suppressed CXCL1 expression and promoted GZMB expression in the glioma microenvironment." (PMID 40636690, 2025). "exploited the property of APOE to effectively cross the blood-brain barrier in vitro to reveal APOE-mediated whole-body nano-delivery of granzyme B and CpG for the enhancement of glioma immunotherapy." (PMID 40292294, 2025). "γδ T cells are a rare subset of T cells with the potential to exert anti-tumor functions in an MHC-independent manner through IFNγ, perforin, and granzyme B release, with anti-glioma activity demonstrated in vitro and in vivo." (PMID 40095115, 2025). "Recent studies reveal a significant overexpression of GZMB in high-grade glioma patients compared to low-grade glioma (LGG) cases." (PMID 38816839, 2024). "Previous studies have reported the involvement of PDIA4, MXRA8, PDLIM4, C9orf64, and GZMB in glioma patients’ poor prognosis through bioinformatics analysis." (PMID 38159261, 2023). "GZMB and HLA-A genes were significantly over-expressed in high-grade glioma patients (p < 0.001, versus low-grade glioma patients)." (PMID 34643804, 2022). "Induced Bregs suppress granzyme B and perforin secretion by the glioma-specific CD8+ T cell, denoting specificity in B cell action against glioma." (PMID 36467419, 2022). "The GZMB gene was observed to be significantly over-expressed in the plasma samples of high-grade glioma patients compared to low-grade glioma patients." (PMID 34643804, 2022). "It is found that the expression of PROS1 had positive correlations with PD-1, PD-L1, PDCD1LG2, CTLA4, HAVCR2, and GZMB (all P <0.05) in glioma." (PMID 36685506, 2022). "In line with this, a previous report reported CD8+ HLA-DR+ T cell activation with the production of IFN-γ and granzyme B after co-culturing with glioma cells." (PMID 34944786, 2021). "In co-cultures of cytotoxic T cells with glioma cell lines (U251 and GL261), vorinostat and sodium butyrate also enhance FAS/FASL and Perforin/Granzyme B pathway-mediated glioma cell apoptosis." (PMID 32560120, 2020). "Patients' CCR5+CD38+HLA-DR+CD8+ T cells were further validated and shown to display increases in CD45RA+CCR7− and T-bet+ accompanied by substantial CD107-a, IFN-γ, and Granzyme B levels in response to glioma cells." (PMID 31649684, 2019). "These positive effects are compatible with increased NK cell effector functions against glioma cells, since NK cells isolated from the brain of glioma-bearing EE mice are both granzyme B- and IFN-γ-positive." (PMID 25818172, 2015). "In the case of glioma cell clearance, granzyme-B is polarized in cytolytic T-cells and delivered to the synaptic interface toward the target glioma cell." (PMID 23641198, 2013).
glioma (continued). "Granzyme-B induces the specific cleavage of alpha tubulin, disrupting the glioma cell cytoskeleton, and leading to CTL-mediated apoptosis of the target cells." (PMID 23641198, 2013). "Finally, PD-1 and GZMB expression levels were assessed in glioma tissues with varying crotonylation levels." (PMID 40636690, 2025). "Therefore, we examined the expression levels of PD-1 and GZMB in glioma samples with different levels of crotonylation modification." (PMID 40636690, 2025). "It has been shown that glioma cells overexpressing galectin-1 are capable to evade NK immune surveillance, whereas the lack of galectin-1 leads to accentuated tumor-killing effects of NK cells by releasing granzyme B." (PMID 38160212, 2024). "The antitumor cytotoxic T cell activity of T-αFGL2 cells against the FGL2-expressing murine glioma cell line, DBT, was evaluated by measuring the proportion of live glioma cells and granzyme B+, interferon γ (IFNγ)+, and tumor necrosis factor α (TNFα)+ T cells." (PMID 36759517, 2023). "Indeed, the expression of A3C displayed positive correlations with CD274, PDCD1, PDCD1LG2, SIGLEC15, CTLA4, HAVCR2, and GZMB in glioma (P < 0.05)." (PMID 37809064, 2023). "Moreover, when the plasma transcriptomic profile of patients with high-grade glioma was compared to patients with low-grade glioma, the GZMB and HLA-A genes were observed to be significantly over-expressed in the high-grade glioma group relative to the low-grade glioma group." (PMID 34643804, 2022). "GD2-CAR/NFATsyn-IL-12 T-cells readily killed GD2+ patient-derived glioma spheroids and secreted IL-12, TNF-α, IFN-γ, Il-2, perforin, and granzyme B upon coculture with GD2+ glioma cells." (PMID 38136398, 2023). "Increased expression of granzyme A, granzyme B, and perforin by intratumoral CD4+ CTLs in gliomas suggests these cells to be a positive prognostic marker for glioma survival." (PMID 37304294, 2023). "In the presence of glioma cells, this CD8+ T cell subset appears to facilitate the enhancement of effector molecules, including CD45RA+CCR7−, T-bet+, CD107a+, IFN-γ+, and granzyme B+." (PMID 31649684, 2019). "Several effector molecules, including CD107a, IFN-γ, and Granzyme B, coincided significantly with CCR5+CD38+HLA-DR+CD8+ T cells after contact with the U87 glioma cells." (PMID 31649684, 2019). "Moreover, when glioma developed in the presence of an equal number of microglial cells, it more rapidly induced higher expression of CD8+ Granzyme B+ T cells (approximately 3%), resulting in stronger tumor restriction." (PMID 40747560, 2025). "Immune-related genes GZMB, HLA-A and BCL2L1 were significantly over-expressed in high-grade glioma patients (p < 0.001, versus low-grade glioma patients) and a concordance between differentially expressed genes in plasma- and glioma-derived RNA was reported." (PMID 37091783, 2023). "Minimal differences were noted in IFNγ, TNFα, Granzyme B, and CD107B expression when comparing CD4+ T cells from glioma patients before and after M032 treatment; however, a significant reduction in IL-4 production between pre- and post-M032 treatment in peripheral blood CD4+ T cells was noted." (PMID 35342877, 2021).
lymphoma (28 papers, 2011 to 2025). A malignant (clonal) proliferation of B- lymphocytes or T- lymphocytes which involves the lymph nodes, bone marrow and/or extranodal sites. "SERPINB9, a serine protease, protects cells from granzyme B associated apoptosis induced by cytotoxic T cells and its expression correlates with clinical outcome of several lymphomas." (PMID 33833385, 2021). "We propose that NKG7 exerts the same function in cytotoxic CD4+ T cells including TFK cells, leading to GZMK-mediated complement activation or GZMB-mediated activation-induced cell death of target – possibly lymphoma – cells." (PMID 41030456, 2025). "The co-expression of cytotoxic molecules (TIA-1, Granzyme B) definitively classifies this lymphoma as deriving from a cytotoxic T-cell subset." (PMID 41357592, 2025). "For this reason, similar to our results with lymphomas, we anticipate that GZMB and GZMA will be the principal axes of cytotoxicity of BCMA CAR T cells targeting MM." (PMID 38307835, 2024). "Histologically, the glans and foreskin revealed neoplastic infiltration of medium-sized lymphoma cells expressing CD56, CD3, granzyme-B, and labeled for EBV-encoded RNA in situ hybridization." (PMID 28874193, 2017). "Yet, despite reduced tumour burden in HIF-1α KO mice, the number of tumour infiltrating NK cells and as well as the expression of the cytotoxic effector molecule Granzyme B in NK cells was lower than in lymphomas from WT littermates." (PMID 29150606, 2017). "The lymphoma cells displayed a CD3ε/CD56/TIA-1/granzyme-B/Perforin-positive and CD20/CD79a/CD4/CD8-negative immunophenotype and positive for Epstein-Barr virus by EBER in situ hybridization." (PMID 24886075, 2014). "Collectively, these findings suggest a differentiation trajectory from TFH to GZMK+ TFK to GZMB+ TFK and finally GZMB+CXCR5–CD4+ T-cell phenotypes during lymphoma progression, reflecting the convergence of cytotoxic CD4+ and CD8+ T cells into exhausted T cells." (PMID 41030456, 2025). "Combinatory treatment with CpG-Stat3 siRNA and CTLA4 antibody in A20 lymphoma tumor-bearing mice significantly increased the percentages of IFNγ and/or granzyme B (GZMB) producing CD4+ T cells and CD8+ T cells in tumors compared to either CpG-Stat3 siRNA or CTLA4 antibody alone." (PMID 39618825, 2024). "Taking into account that anti-PD-1 immunotherapy may affect HSP90 expression in NK cells, we assessed the effect of HSP90 downregulation on the degranulation response, granzyme B and IFNγ production in NK cells of lymphoma patients." (PMID 35572591, 2022). "The distribution of CSF1R protein in tonsil was also compared, using double immunoenzymatic labelling technique, with other markers of the microenvironment known to be associated with lymphoma pathogenesis, for example, FOXP3, PD-1 and the cytotoxic marker Granzyme B." (PMID 26066800, 2015). "Furthermore, the expression of CD3, CD56, TIA-1 and Granzyme B differentiates NK/T-cell lymphoma from other types of lymphoma." (PMID 25013513, 2014). "Granzyme B polymorphism did not have any effect on the transplant outcomes in patients with lymphoid malignancies consisting of acute lymphoid leukemia and malignant lymphoma." (PMID 21886827, 2011). "One possible cause for downregulation of granzyme B might be the direct interactions between the NK cells and CTCL cells in the local microenvironment, underlining the importance to investigate anti-lymphoma immune responses at the site of the lymphoma." (PMID 37691935, 2023). "Here, we show that lymphoma samples contain cytotoxic CD4+ T cells, which were predominantly NKG7/TIA-1+GZMK+ TFH-like in FL and TIA-1+GZMK+ and/or GZMB+ within the CXCR5+PD-1+ and CXCR5–PD-1+ subpopulations of DLBCL." (PMID 41030456, 2025). "There, granzymes mediate distinct cytotoxic mechanisms: GZMB provokes canonical apoptosis by activating the caspase cascade, consistent with the ability of isolated and activated TFK cells to kill lymphoma B cells by inducing apoptosis." (PMID 41030456, 2025).